KRAS (KRas proto-oncogene, GTPase)
Diseases named in the same sentence as KRAS in open-access papers (continued):
Sharing a sentence is not in itself a finding about the gene and the disease.
colorectal cancer (continued). "Later, examination of two other colorectal cancer cell lines including HCT116 (abnormal KRAS allele) and HKe3 (the kind of wild KRAS allele) went on, with the findings obtained from sequencing confirming the fact that overall expression of circRNAs was higher in HKe3 compared with HCT116." (PMID 31481095, 2019). "About 40% of colorectal cancers are KRAS mutated, 5% NRAS mutated, and rarely HRAS mutated." (PMID 31803624, 2019). "For example, ATT using multiple T cell Receptors (TCRs), which recognize HLA-A*02:01+ spliced epitopes carrying KRAS mutations, could treat around 30% of pancreatic adenocarcinoma patients and a large portion of colorectal carcinoma patients." (PMID 31803176, 2019). "These two properties of eK8 could represent key molecular mechanisms leading to the formation of metastases, making eK8 a relevant target in colorectal cancer, including KRAS-mutant diseases that are associated with resistance to EGFR inhibition." (PMID 30453567, 2018). "The presence of APC mutations as an alternative to CTNNB1 mutations in some POLE‐mutant endometrial cancers is an exemplar, and there are likely to be others, such as NF1 and RB1 mutations in endometrial cancer and atypical (Q61P, K117 N, and A146T) KRAS mutations in colorectal cancer." (PMID 29604063, 2018). "Moreover, mutation in KRAS gene which is linked with the colorectal cancer initiation and progression further interferes with the antibody therapies." (PMID 29484148, 2018). "We also observed that the iQC index could be used to obtain a diagnosis using other cancer type samples (colorectal cancer) and other diagnostic kits, including the ddPCR-based KRAS mutation test and the cobas KRAS mutation test." (PMID 29323170, 2018). "Whereas a select few assays, for example, APC or KRAS mutations in colorectal cancer, BRAF in melanoma encompass a significant proportion of patients, and are thus reliable aberrations to use a surrogate for tumour fraction, the equivalent targets have yet to be demonstrated in MIBC." (PMID 30158468, 2018). "In colorectal cancer, KRAS mutations have been detected in 40% of cases." (PMID 29896883, 2018). "In colorectal cancer (CRC) approximately 30% to 50% of tumors have KRAS mutations that occur early in the tumorigenesis pathway, so the detection of KRAS mutations is useful for early diagnosis, prognosis and evaluation of the therapeutic outcome in cancer treatment." (PMID 30562355, 2018). "In line with this hypothesis, PTPRK-RSPO3-positive colorectal cancers are positive for KRAS or BRAF mutations and are microsatellite-stable." (PMID 29652830, 2018). "KRAS mutations have been frequently observed in histologically normal lung tissue adjacent to lung tumors, as well as normal mucosa adjacent to KRAS mutation–positive colorectal cancer." (PMID 29300727, 2018). "KRAS-mutated colorectal cancer is related to the RAS/ERK or PI3K/AKT pathways." (PMID 30577618, 2018). "KRAS mutation was significantly associated with mucinous production (p < 0.05), tumor stage (p < 0.05) and was higher in non-smokers (p < 0.05) and patients with a family history of colorectal carcinoma (p < 0.05)." (PMID 29423347, 2018). "In colorectal cancers, mutant KRAS is associated with resistance to CET." (PMID 27783105, 2017). "In colorectal cancer, increasing evidence exists that the appearance of new KRAS mutations during treatment with agents targeting the EGFR (like cetuximab or panitumumab) may be linked to an acquired resistance to anti-EGFR therapy." (PMID 28549417, 2017). "KRAS mutation is an early event in colorectal cancer carcinogenesis." (PMID 28445136, 2017). "In colorectal cancer cells, exosomal loading has been shown to be dependent on KRAS mutational status, with mutant KRAS cells releasing higher levels of miR-100 and wild-type KRAS cells releasing higher levels of miR-10 into the exosomal fractions, through a mechanism requiring nSMAse." (PMID 27872688, 2017).
colorectal cancer (continued). "Keeping in mind that KRAS mutated ctDNA from colorectal cancer patients showed with a high quantity of low-size fragments (< 80 bp) discrepancy of mutational status might be explained by different primer amplicon length." (PMID 29156792, 2017). "In the case of cetuximab and panitumumab, antibodies targeting the epidermal growth factor receptor (EGFR), prospective and retrospective analyses in patients with colorectal cancer (CRC) established the importance of KRAS mutations on sensitivity to these agents." (PMID 28981524, 2017). "Approximately 40–60% of colorectal cancers harbor a KRAS mutation." (PMID 29202108, 2017). "However, the likelihood of the presence of two or more mutations in the same codon of the KRAS gene is too rare and the reports of these co-occurrence mutations have little been documented in colorectal cancer." (PMID 28580315, 2017). "This is also consistent with the finding that KRAS mutation may be a good biomarker of MEK inhibitor sensitivity for treating colorectal cancer." (PMID 27965461, 2017). "Furthermore, PLCD1 inhibits the epithelial-mesenchymal transition (EMT) of KRAS-mutated colorectal cancers." (PMID 28423710, 2017). "We further investigated whether RBP4 expression was associated with aggressive presentations of colorectal cancer using classifications based on low or stable microsatellite instability and constitutively active KRAS mutations." (PMID 28689994, 2017). "However, it is in colorectal cancer (CRC) that KRAS mutations have recently acquired most clinical significance." (PMID 28636636, 2017). "In addition, we investigated G12S known to occur with low frequency of 4.9 – 5.7% in KRAS mutated colorectal cancers." (PMID 29156792, 2017). "In addition, the future clinical trials related to colorectal cancer, should specifically consider the eligibility of patients with concomitant KRAS and BRAF-mutated tumors." (PMID 28580315, 2017). "To assess the analytical sensitivity of the asymmetric barcode adapter, we constructed an additional NGS library using genomic DNA from the CEU HapMap sample NA12878 as a reference and a colorectal cancer cell line (SW480) known to harbor the KRAS G12V mutation as a positive control." (PMID 28462938, 2017). "Indeed, PLCD1 induces cell cycle arrest by inhibiting Akt signalling in ESCC, and suppresses EMT through ERK signalling in KRAS-mutated colorectal cancers." (PMID 28423710, 2017). "For the first time, we have detected KRAS mutations in colorectal carcinoma with OM." (PMID 29029440, 2017). "While missense mutations at G12, G13, and Q61 in KRAS are canonical drivers of lung, pancreas, and colorectal cancers, overexpression of wild-type KRAS has been observed in head and neck, endometrial, ovarian, testicular, lung, gastric, colon, and bladder cancers." (PMID 27684555, 2016). "As conclusion the IdyllaTM KRAS Mutation Test can be applied as routine tool in any clinical setting, without needing molecular infrastructure or expertise, to guide the personalized treatment of colorectal cancer patients." (PMID 27685259, 2016). "In conclusion, KRAS G12V mutation is detectable in plasma of colorectal cancer patients by ddPCR and could be used as a non-invasive biomarker." (PMID 27043547, 2016). "Some studies have investigated KRAS mutations from ctDNA in colorectal cancer patients." (PMID 26918901, 2016). "In addition, k-means clustering and the Calinski criterion showed that k = 3 gave the optimal number of clusters, which indicated low dependence of metabolism of colorectal cancer on KRAS mutation alone." (PMID 27924922, 2016).
colorectal cancer (continued). "Analysis of extracellular RNA in isogenic cell lines differing only in KRAS status revealed that secretion of a sub-population of miRNAs is decreased in colorectal cancer cells harboring an activating KRAS mutation whereas other miRNAs are secreted at equivalent levels irrespective of KRAS status." (PMID 27559612, 2016). "KRAS mutations occur in 30–40% of all cases of human colorectal cancer (CRC)." (PMID 27526107, 2016). "To evaluate the actual effectiveness of our two-step analysis platform in a routine diagnostic setting, we reviewed effort and outcome of KRAS codon 12/13 mutation testing in 120 independent colorectal cancer samples that were examined consecutively in our laboratory according to this concept." (PMID 27485514, 2016). "KRAS G12V mutation is detectable in plasma of colorectal cancer patients by ddPCR and could be used as a non-invasive biomarker of drug resistance during disease progression." (PMID 27043547, 2016). "However, in women only high WHR was significantly associated with an increased risk of KRAS-mutated colorectal cancers." (PMID 26801617, 2016). "KRAS point mutations have been studied in terms of pathogenesis and progression in colorectal cancers and their identification has recently been shown to be clinically useful as an indicator of cetuximab therapeutic effect, represented by overall survival and progression-free survival." (PMID 26999437, 2016). "The average KRAS mutation rate was 26% in colorectal cancer with varied signet-ring cell component." (PMID 27300552, 2016). "An analysis of the evolutionary dynamics of cancer cells with KRAS mutations in patients with colorectal cancer after treatment demonstrated that these mutations had been present before the initiation of EGFR blockade, in rare subclones harboring approximately thousands of cancer cells." (PMID 26912072, 2016). "Somatic activating mutations in KRAS or NRAS are present in up to 52% of colorectal cancer (CRC), causing constitutive activation of the RAF/MEK/ERK signaling pathway independent of upstream receptor tyrosine kinases like the epidermal growth factor receptor (EGFR)." (PMID 27167191, 2016). "To study how circRNAs might be regulated during colorectal cancer progression, we used three isogenic colon cancer cell lines that differ only in KRAS mutation status." (PMID 27892494, 2016). "Correlation between KRAS mutation and Patients’ characteristics of 270 colorectal carcinomas." (PMID 26812617, 2016). "KRAS mutation analysis relative to NM reference DNA in colorectal carcinoma FFPE tissues." (PMID 27632281, 2016). "At present, however, only an arbitrary section of the primary tumor is analyzed for KRAS mutations in colorectal cancer patients and the genomic heterogeneity of metastatic cells—the actual targets of systemic therapy–is not taken into consideration for therapy decisions." (PMID 25398926, 2015). "Moreover, further studies demonstrated that for KRAS-mutated tumors (∼40% of colorectal cancer), anti-EGFR antibodies cause harm and decrease survival." (PMID 26320181, 2015). "Notably, MLH1 and MGMT have been previously associated with two distinct methylation landscapes in colorectal cancer that exhibited important differences in terms of KRAS and APC mutation frequency." (PMID 25960768, 2015). "Moreover, we observed a similar frequency of somatic mutations for KRAS oncogene to overall sporadic colorectal cancers that correspond to 40%." (PMID 26557847, 2015). "Mutations in the KRAS proto-oncogene are now widely recognized to be predictive for primary as well as acquired resistance to tailored therapy with anti-EGFR antibodies in colorectal cancer." (PMID 25568935, 2015). "Findings from the VICTOR trial showing that KRAS mutant tumors are associated with an increased risk of lung relapse in CRC patients supported the role of chest imaging in surveillance of colorectal cancer patients, particularly of those with resected primary mutated KRAS carcinoma." (PMID 25888291, 2015).
colorectal cancer (continued). "The KRAS transversion mutations in patients with NSCLC correspond to a greater frequency of the G12C variant compared with the more predominant G12D variant found in patients with colorectal cancer." (PMID 25962919, 2015). "Colorectal cancer cells with either a KRAS or BRAF mutation exhibited high expression levels of the glucose transporter-1 (GLUT1) gene and were able to survive in low glucose environments; whereas, the wild type cells exhibited low levels of GLUT1 and were not viable in low glucose conditions." (PMID 25856378, 2015). "In the case of colorectal cancer, discovery of the role of KRAS mutation in the resistance to the EGFR-targeting antibody (cetuximab or panitumumab) helped to identify a group of patients that can benefit from this kind of treatment (patients with wild-type KRAS)." (PMID 26320181, 2015). "KRAS mutations were detected at a frequency of 35.3% (53/150) in colorectal cancer specimens." (PMID 25674493, 2015). "In colorectal cancer, the presence of the KRAS mutation was associated with upregulation of miR-127-3p, miR-92a, and miR-486-3p and downregulation of miR-378, which constituted a miRNA signature capable of predicting colorectal cancers resistant to EGFR antagonists." (PMID 25874201, 2015). "Given the known resistance mechanisms of MEK inhibition in colorectal cancer, we hypothesized that tumors with known KRAS/NRAS or BRAF mutations that were PIK3CA wild-type would exhibit greater sensitivity to MEK inhibition." (PMID 26439693, 2015). "Since RAS isoforms have been implicated in autophagy regulation and mutation of the KRAS oncogene is highly frequent in colorectal cancer (CRC), we questioned whether/how mutant KRAS alleles regulate autophagy in CRC and its implications." (PMID 26418750, 2015). "Many colorectal cancer cells have mutations in a gene that encodes a protein called KRAS." (PMID 26132860, 2015). "Mutations in KRAS were most common in pancreatic cancer followed by colorectal cancer." (PMID 26015395, 2015). "Interestingly, recent findings have shown that in the setting of colorectal cancer, at least 12 subtypes of KRAS mutations across codons 12 and 13 associate with variable yet negative efficacy of cetuximab." (PMID 25962919, 2015). "In addition, mucinous tumors were more likely than other type of colorectal carcinomas in either KRAS codon 12 or 13 mutated tumors." (PMID 25929517, 2015). "Mutations of KRAS occurred in 34.8% of colorectal carcinomas." (PMID 25929517, 2015). "In colorectal carcinoma KRAS resistance mutations were detected with an allele frequency of 0.2%." (PMID 25886408, 2015). "It remains to be investigated why KRAS mutations are associated with CIMP-low in colorectal cancer." (PMID 24885062, 2014). "Our data from over 1200 colorectal cancers demonstrate that KRAS codon 61 or 146 hotspot mutations are present in approximately up to 5% of colorectal cancers, and those cancers exhibit similar clinicopathological and molecular features to cancers with KRAS codon 12 or 13 mutation." (PMID 24885062, 2014). "We detected KRAS mutations in 505 (40%) cases in 1267 colorectal cancers." (PMID 24885062, 2014). "This speculation is in keeping with the finding that mutations in exon 4 of KRAS predict for a more favorable clinical outcome in patients with colorectal cancer." (PMID 25412182, 2014). "In this article, we report 7 novel KRAS gene mutations discovered while retrospectively studying the prevalence and pattern of KRAS mutations in cancerous tissue obtained from 56 Saudi sporadic colorectal cancer patients from the Eastern Province." (PMID 25412182, 2014). "A similar case seems to be with the KRAS mutation in colorectal cancer." (PMID 24461084, 2014). "Accordingly, the prognostic associations of KRAS mutations in colorectal cancer may vary by specific mutation." (PMID 24885062, 2014). "KRAS mutations have a high prevalence in colorectal cancers." (PMID 24875049, 2014).
colorectal cancer (continued). "Therefore, determining the KRAS mutational status of tumor samples has become an essential tool in managing patients with colorectal cancers." (PMID 25713627, 2014). "We therefore investigated the clinicopathological, molecular, and prognostic characteristics of tumors harboring KRAS codon 61 and 146 mutations, utilizing a molecular pathological epidemiology database of 1267 colorectal cancers from two U.S. nationwide prospective cohort studies." (PMID 24885062, 2014). "Our discovery of novel exon 4 KRAS mutations that are, so far, unique to Saudi colorectal cancer patients may be attributed to environmental factors and/or racial/ethnic variations due to genetic differences." (PMID 25412182, 2014). "Similarly, colorectal cancer patients with low abundance of KRAS mutation have been reported to benefit from EGFR antibody therapy." (PMID 24398248, 2014). "The prognostic value of KRAS mutation in colorectal cancer remains controversial." (PMID 24885062, 2014). "KRAS mutations have been widely reported in many cancers including lung and colorectal cancers." (PMID 25222473, 2014). "A first excellent example may become the recently developed non-invasive multitarget stool DNA test (CologuardTM) for colorectal cancer screening that includes besides KRAS mutation analysis, detection of the methylation status of the NDRG4 and BMP3 genes." (PMID 27600342, 2014). "Here, we describe a review and meta-analysis of the relationship between KRAS-LCS6 genotype with overall and disease-free survival among colorectal cancer patients in an effort to add clarity to the potential implications, if any, of this functional genetic KRAS variant on clinical management." (PMID 24890702, 2014). "If one compares pediatric cancers to colorectal cancer which have an incidence of 400 cases per million in the USA, and a bias toward particular predictive biomarkers such as KRAS or NRAS mutation the feasibility of applying this technique to colorectal and other common cancers is clear." (PMID 25988159, 2014). "Numerous studies have reported the frequency of KRAS gene mutations in colorectal cancer." (PMID 25412182, 2014). "Our discovery of novel Exon 4 KRAS mutations that are, so far, unique to Saudi colorectal cancer patients from the Eastern Province may be attributed to environmental factors and/or racial/ethnic variations due to genetic differences." (PMID 25412182, 2014). "Moreover, about 70% of colorectal cancers with a KRAS mutation also have an excess of small chemical marks on other genes, some of which are known to suppress the growth of tumors." (PMID 24623306, 2014). "Overall KRAS mutation prevalence in colorectal cancers was 40% (=505/1267)." (PMID 24885062, 2014). "Despite growing clinical relevance, the clinicopathological and molecular features of colorectal cancers with KRAS codon 61 or 146 mutation remain largely unknown." (PMID 24885062, 2014). "Moreover, we examined two additional KRAS-mutated cell lines, the pancreatic cancer cell line MIAPaCa-2 and colorectal cancer cell line SW480." (PMID 25422890, 2014). "Colorectal cancers can be classified using mutations in oncogenes such as KRAS, BRAF and PIK3CA." (PMID 24885062, 2014). "In colorectal cancer, for example, mutations in KRAS can cause resistance to both drugs." (PMID 23990977, 2013). "Notably, the KRAS mutation spectrum in colorectal cancer is quite different from that in lung cancer of smokers; G to T transversion is most common in lung cancer, while G to A transition is most common in colorectal cancer." (PMID 24179496, 2013). "The potential of KRAS codon 12/13 mutations as effective molecular markers for drug selection has received considerable attention leading to their use in the routine care of patients with colorectal cancer." (PMID 23536897, 2013).